ARID1A (AT-rich interaction domain 1A)
Diseases named in the same sentence as ARID1A in open-access papers (continued):
Sharing a sentence is not in itself a finding about the gene and the disease.
Obesity (2 papers, 2018 to 2020). Accumulation of substantial excess body fat. "Subsequent meta-analysis of summary results from stage 1 and stage 2 revealed significant association of rs6598860 (P = 1.58 × 10−4) and rs4589135 in ARID1A (P = 3.72 × 10−4) with overweight/obesity after multiple testing correction (P = 6.33 × 10−4)." (PMID 29500370, 2018). "Our results demonstrate the associations of two SNPs in ARID1A (rs6598860 and rs4589135) with the risk of overweight/obesity in urban Indian adolescents." (PMID 29500370, 2018). "The top signals for overweight/obesity were identified at rs4589135 [P = 1.2 × 10−4] and rs6598860 [P = 7.8 × 10−4] in ARID1A gene." (PMID 29500370, 2018). "Our study revealed significant associations of two variants rs6598860 (OR = 1.27, P = 1.58 × 10–4) and rs4589135 (OR = 1.22, P = 3.72 × 10–4) in ARID1A with overweight/obesity." (PMID 29500370, 2018). "We replicated the associations of rs6598860 (P = 0.04) in ARID1A and rs17003998 in SMARCE1 (P = 0.01) with overweight/obesity." (PMID 29500370, 2018). "In conclusion, our data revealed that common variants of ARID1A and KAT2B are associated with increased susceptibility to overweight/obesity in Indian urban adolescents." (PMID 29500370, 2018). "These evidences suggest that ARID1A may affect obesity through cytokines (IL6), adipokines (leptins) or lipids mediated lipid pathways." (PMID 29500370, 2018). "In conclusion, our study suggests a potential role of ARID1A and KAT2B genes in the development of obesity in adolescents and provides leads for further investigations." (PMID 29500370, 2018).
olfactory neuroblastoma (2 papers, 2022 to 2023). An olfactory neuroblastoma arising in the paranasal sinus. "The neuroectodermal differentiation of specimens from the NEC-like IDH2 (FDR < 0.001) and NEC-like SMARCA4/ARID1A class (FDR < 0.001) as well as olfactory neuroblastomas (FDR < 0.001) was reflected in their similarity with pulmonary neuroendocrine cells (PNEC)." (PMID 36443295, 2022). "In contrast, cytokeratin 18 (KRT18) was strongly overexpressed in both NEC-like IDH2 and NEC-like SMARCA4/ARID1A cancers but not in olfactory neuroblastoma." (PMID 36443295, 2022).
oligodendroglioma (2 papers, 2019). A well-differentiated (WHO grade II), diffusely infiltrating neuroglial tumor, typically located in the cerebral hemispheres. "Variants in tumor associated genes not typically associated with oligodendroglioma were also found, such as missense variants in TET1 (NM_030625:c.4399G>A; p.Glu1467Lys) and TGFBR2 (NM_003242:c.426G>C; p.Glu142Asp as well as a frameshift variant in ARID1A (NM_006015:c." (PMID 31217899, 2019).
pancreatic neuroendocrine tumor (2 papers, 2020). Pancreatic endocrine tumor, also known as pancreatic neuroendocrine tumor (PNET), describes a group of endocrine tumors originating in the pancreas that are usually indolent and benign, but may have the potential to be malignant. "In the COSMIC database as well, well-differentiated indolent pancreatic neuroendocrine tumors, with a proliferation rate < 3% Ki-67, carry a ~20% ARID1A mutation rate, much higher than 5.35% aggressive PDAC." (PMID 32967217, 2020).
renal carcinoma (2 papers, 2021 to 2025). A carcinoma arising from the epithelium of the renal parenchyma or the renal pelvis. "The ARID1A gene is a tumor suppressor encoding the ARID1A protein, whose inactivating mutation is an essential element in the development of many types of tumors, including ovarian, breast, and renal cancers etc." (PMID 40548109, 2025).
schwannoma (2 papers, 2024 to 2025). A benign, usually encapsulated slow growing tumor composed of Schwann cells. "An exome study in humans found that 37/125 (29%) of schwannomas have NS mutations in ARID1A or ARID1B." (PMID 38232086, 2024). "It is possible that the significance of Arid1a to schwannoma progression may be similar in the rat." (PMID 38232086, 2024). "Other recurrently altered genes reported in schwannomas include LATS1, LATS2, ARID1A, ARID1B and DDR1." (PMID 41300852, 2025).
sinonasal carcinoma (2 papers, 2021 to 2022). "Indeed, molecularly distinct subtypes of sinonasal carcinomas, including SMARCB1-INI1 or SMARCA4 deficient sinonasal carcinoma, isocitrate dehydrogenase (IDH)-mutant SNUC, ARID1A mutant PDSNCs, and NUT carcinomas, have recently been proposed as separate entities." (PMID 34638515, 2021). "Indeed, molecularly distinct subtypes of sinonasal carcinomas, including SMARCB1-INI1 or SMARCA4 deficient sinonasal carcinoma, isocitrate dehydrogenase (IDH)-mutant SNUC, ARID1A mutant PDSNCs, and NUT carcinomas (harboring NUT-variant fusions), have recently been proposed as separate entities." (PMID 34638515, 2021).
small cell lung carcinoma (2 papers, 2022 to 2024). Small cell lung cancer (SCLC) is a highly aggressive malignant neoplasm, accounting for 10-15% of lung cancer cases, characterized byrapid growth, and early metastasis. "When compared to small-cell lung cancer (SCLC), SCNCC samples demonstrated notably higher frequencies of genomic alterations in PIK3CA (24% vs. 5.1%), MYC (12.7% vs. 6.3%), ARID1A (10.1% vs. 4.2%), and MSI-High (3.1% vs. 0.004%)." (PMID 38793044, 2024).
steatosis (2 papers, 2024 to 2026). Increased lipid within the cytoplasm of cells. "A marked steatosis of inactivated HNF-1α HAs was in fact substituted by an enriched vascularity and an apparently more aggressive phenotype in the ARID1A-mutated HA, which is consistent with reports of malignant transformation of HNF1A-related HAs." (PMID 39408812, 2024).
teratoma (2 papers, 2020 to 2022). A non-seminomatous germ cell tumor characterized by the presence of various tissues which correspond to the different germinal layers (endoderm, mesoderm, and ectoderm). "ARID1A expression was also detectable in pediatric type I GCTs (immature and mature teratoma, yolk-sac tumors)." (PMID 32272809, 2020).
vulvar carcinoma (2 papers, 2015 to 2024). "The downregulation of Arid1a in endometrial and vulvar cancer in the series of patients of our study, is consistent with these findings." (PMID 26559525, 2015).
-dependent (1 paper, 2022). "ARID1A co-regulates a large subset of genes regulated by estrogen, which may explain why ARID1A mutations are common in estrogen-dependent gynecologic diseases and cancers, wherein ARID1A mutations are observed in the epithelial compartment." (PMID 35326450, 2022).
acral melanoma (1 paper, 2022). "Also, it has been reported that subungual melanoma harbors more distinct genomic alterations including CARD11, ARID2, ARID1A, ARID1B, PTPRB, and PTPRK genes, compared with acral melanoma." (PMID 35484605, 2022).
acute lymphoid leukemia (1 paper, 2015). "Downregulation of the BAF complex subunits SMARCA4, ARID1A, and SMARCB1 has been associated with glucocorticoid-resistance in acute lymphoid leukemia (ALL)." (PMID 25789315, 2015).
age (1 paper, 2026). A temporal measurement of the time period elapsed since an identifiable point in the life cycle of an organism. "BAF250a (ARID1A) safeguards mitochondrial FAO by maintaining chromatin accessibility at Acox1 and Cpt1a promoters, with hepatocyte‐specific knockout mice developing age‐dependent steatohepatitis and HCC." (PMID 41578412, 2026).
alcohol abuse (1 paper, 2024). The use of alcoholic beverages to excess, either on individual occasions ("binge drinking") or as a regular practice.
asthma (1 paper, 2025). "The asthma-related gene set, which is closely associated with type 2 immunity, was enriched in all Arid1a mutation-associated mice." (PMID 40761291, 2025). "In addition, gene sets related to the PI3K/AKT pathway and asthma were enriched in ARID1A-low cells." (PMID 40761291, 2025).
autism spectrum disorder (1 paper, 2022). A spectrum of developmental disorders that includes autism, and Asperger syndrome. "Mutations in ARID1A are associated with craniofacial abnormalities, while mutations in ARID1B are associated with autism spectrum disorder and SCZ." (PMID 35444632, 2022).
B-cell neoplasm (1 paper, 2025). A group of heterogeneous lymphoid tumors generally expressing one or more B-cell antigens or representing malignant transformations of B-lymphocytes. "Whole-exome sequencing revealed an elevated somatic copy number alteration burden and pathogenic variants in ARID1A, KMT2D, BCL7A, PTPN11, and NUP214, suggesting disruptions in chromatin remodeling, B-cell neoplasm pathogenesis, and oncogenic signaling driving the tumorigenesis." (PMID 41378284, 2025).
blastic plasmacytoid dendritic cell neoplasm (1 paper, 2023). "In blastic plasmacytoid dendritic cell neoplasm (BPDCN), mutations (mostly loss-of-function) and deletions in ARID1A seem to be recurrent, although cohort sizes have been low (8 altered patients, combined N = 70)." (PMID 36810086, 2023).
bone metastasis (1 paper, 2020). Transfer of a neoplasm from its primary site to bones. "Patients with loss of function mutations of ARID1A (72.7 vs. 143.6%, P = 0.02, adj P = 0.13) were more likely to develop bone metastasis." (PMID 32695676, 2020).
bone osteosarcoma (1 paper, 2019). A usually aggressive malignant bone-forming mesenchymal neoplasm arising from the bone. "It has been shown that ARID1A promotes NHEJ activity by facilitating the accumulation of Ku70/Ku80 proteins at DSBs, conferring resistance to UV, ionizing radiation, and cisplatin in lung and bone osteosarcoma cells." (PMID 31847141, 2019).
carcinoma in situ (1 paper, 2018). "Interestingly, ARID1A alterations are present in both subgroups of MIBC, i.e. in cases potentially arising from high-grade papillary carcinomas (pTa HG) (35/133 = 26%) and tumors of non-papillary origin developing from carcinoma in situ (67/269 = 25%)." (PMID 30138427, 2018).
cardiac tumors (1 paper, 2024). "Mutations were found in Arid1a, Setd2, Nf1 and Egfr in all cardiac tumors and in Pdgfra for eight of the tumors." (PMID 38232086, 2024).
cervical tumors (1 paper, 2021).
cognitive disorder (1 paper, 2022). A disease affects cognitive processes. "Together, these data establish the genetic basis of the pathophysiological role of ARID1A in CSS and indicate the therapeutic potential of acetate for cognitive disorders with ARID1A haploinsufficiency." (PMID 36385502, 2022).
Cognitive impairment (1 paper, 2022). Abnormal cognition is characterized by deficits in thinking, reasoning, or remembering. "In this study, we report that the haploinsufficiency of ARID1A in excitatory neurons causes cognitive impairment and defects in hippocampal synaptic transmission and dendritic morphology in mice." (PMID 36385502, 2022). "More importantly, we found that the addition of acetate, which increases H3K27 acetylation, leads to the recovery of GABA type A receptor and synaptic function and improves cognitive impairment in Arid1a haploinsufficiency mice and hESC ARID1A null neurons." (PMID 36385502, 2022).
colitis (1 paper, 2025). Inflammation of the colon. "Notably, the short-term advantage provided by the immune exclusion phenotype associated with mutant ARID1A clones could also confer a pro-oncogenic function long-term, explaining the role of ARID1A as a driver gene in colitis-associated cancer." (PMID 39920335, 2025).
Cornelia de Lange syndrome (1 paper, 2021). A rare syndrome characterized by low birth weight, delayed growth, intellectual disabillity, behavioral problems, and a distinctive facial appearance (thin, arched eyebrows, low set ears, small teeth, and small nose). "Amongst these OTUD5 substrates are ARID1A/B, HDAC2, and HCF1, mutations of which underlie different developmental disorders (Coffin–Siris and Cornelia de Lange syndromes, X-linked mental retardation 3) that exhibit considerable phenotypic overlap with LINKED patients." (PMID 33335288, 2021).
corpus callosum agenesis (1 paper, 2023). "Though malformations such as corpus callosum agenesis have been described in CSS caused by pathogenic variants in ARID1A, prenatal anomalies are rare with almost all CSS patients ascertained in postnatal period." (PMID 36859317, 2023).
diffuse large B-cell lymphoma (1 paper, 2024). "Among BAF subunits, ARID1A, ARID1B, and SMARCA4 are each mutated in ~10% of Diffuse Large B-Cell Lymphomas (DLBCL), which are thought to originate from malignant transformation of germinal center B cells." (PMID 38313292, 2024).
dysplasia (1 paper, 2023). A usually neoplastic transformation of the cell, associated with altered architectural tissue patterns.
eccrine adenocarcinoma (1 paper, 2024). "One other patient had a clear ARID1A loss on IHC: a patient with eccrine adenocarcinoma with ARID1A stop-gain mutation (R693X, resulting in truncated protein expression) and H score of 0 with CDKN2A deletion (240 mg BD; SD, 34 weeks)." (PMID 37934611, 2024).
erythrocytosis (1 paper, 2020). "To determine whether erythrocytosis in [Apc-Arid1a]ko-focal mice could be due to dysregulation of this key hematological regulator, we examined Epo transcript and protein levels within the entire liver and the plasma fraction, respectively." (PMID 33084574, 2020).
Gastric Metaplasia (1 paper, 2025). Intestinal metaplasia of the gastric mucosa is an intermediate precancerous gastric lesion in the gastric cancer cascade from chronic gastritis and atrophy to dysplasia and adenocarcinoma. "In addition, markers of gastric metaplasia, including Tff2, Cd44, and Clu, were upregulated in Arid1a-mutated SPGs, PPGs, and even mature pit cell clusters." (PMID 40761291, 2025).
growth disorders (1 paper, 2023). "All these variants were identified in genes already associated with growth disorders: PROKR2 (N = 2), PTPN11 (N = 6), ANKRD11 (N = 1), NPR2 (N = 1), NF1 (N = 1), ACAN (N = 1), GH1 (N = 1), FBN1 (N = 1), COMP (N = 1), IGF1R (N = 1), ARID1A (N = 1), and CASR (N = 1)." (PMID 37605180, 2023).
Helicobacter pylori (1 paper, 2020). "Patients with EMAST+ tumors had fewer Borrmann type 3 and 4 tumors, fewer Helicobacter pylori (HP) infections, earlier pathological T categories, and more genetic mutations in the PI3K/AKT pathway and in ARID1A than those with EMAST− tumors." (PMID 32120855, 2020).
immune deficiencies (1 paper, 2025). "These immune deficiencies may underline the poor DFS observed in dCRT-treated ARID1A/B2M-mutant patients." (PMID 40536270, 2025).
insulinomas (1 paper, 2020). "We determined protein expression of ARX and PDX1 together with ATRX, DAXX, ARID1A, and H3K36me3 by immunohistochemistry, as well as ALT and CDKN2A deletions by fluorescence in situ hybridization (FISH), in a cohort of clinically defined sporadic insulinomas." (PMID 32103422, 2020). "Insulin, glucagon, ARID1A, H3K36me3 IHC, and CDKN2A FISH were only tested on 31 cases, as for the last four insulinoma cases, no unstained TMA slides were available." (PMID 32103422, 2020).
ischemia reperfusion injury (1 paper, 2023). Adverse functional, metabolic, or structural changes in ischemic tissues resulting from the restoration of blood flow to the tissue (reperfusion), including swelling; hemorrhage; necrosis; and damage from free radicals. "In mouse hearts subjected to ischemia-reperfusion injury (IR), Arid1a expression was induced 1 and 3 days after injury." (PMID 37543677, 2023).
kidney tumors (1 paper, 2024).
lentivirus infection (1 paper, 2022). Virus diseases caused by the Lentivirus genus. "The EGFR-mutant human LUAD cell line HCC4006 was implanted with sh-RNA for ARID1A and the NC vector after lentivirus infection." (PMID 36229854, 2022).
lymphoid tumors (1 paper, 2025). "When combined with the BCL2 oncogene, Arid1a loss indeed promoted progression of lymphoid tumors in mice." (PMID 39843653, 2025).
mantle cell lymphoma (1 paper, 2023). Mantle cell lymphoma is a rare form of malignant non-Hodgkin lymphoma affecting B lymphocytes in the lymph nodes in a region called the ``mantle zone''. "In mantle cell lymphoma (MCL), recurrent mutations have been observed in SMARCA4 (mutation frequency ~ 6-10%), ARID2, ARID1A, and ARID1B (mutation frequency ~ 3-6% each)." (PMID 36810086, 2023).
marginal zone lymphoma (1 paper, 2023). A usually indolent mature B-cell lymphoma, arising from the marginal zone of lymphoid tissues. "In marginal zone lymphoma (MZL), recurrent mutations have been reported in ARID1A (7%) and ARID1B (4%)." (PMID 36810086, 2023).
metaplastic breast carcinoma (1 paper, 2019). A group of invasive breast carcinomas characterized by the presence of an adenocarcinomatous component which is admixed with a dominant component that is composed of squamous cells, spindle cells, or mesenchymal cells. "However, the occurrence of ARID1A mutations seems to be rare in triple-negative IDC-NST tumors and more frequently in metaplastic breast carcinoma (1 vs 11%)." (PMID 31481116, 2019).
metastatic prostate carcinoma (1 paper, 2023). A carcinoma that arises from the prostate gland and has spread to other anatomic sites. "We predicted monoallelic ARID1A LOF (PR-AUC-E = 0.208; AUROC = 0.72) by depletion of SBS signature 8 mutations in metastatic prostate cancer." (PMID 36883553, 2023).
multiple endocrine neoplasia type 1 (1 paper, 2025). An autosomal dominant tumor predisposition syndrome caused by pathogenic variants in the MEN1 gene, characterized by an increased risk of tumors of the parathyroid glands, pituitary gland, and foregut neuroendocrine tumors (most commonly pancreatic islet cells). "The most commonly mutated genes include SWI/SNF (SWItch/Sucrose Non-Fermentable), MEN-1 (Multiple Endocrine Neoplasia type 1), PSIP1 (PC4 And SRSF1 Interacting Protein 1), and ARID1A (AT-Rich Interaction Domain 1A)." (PMID 40426858, 2025).
myocardial infarction (1 paper, 2023). Gross necrosis of the myocardium, as a result of interruption of the blood supply to the area, as in coronary thrombosis. "Upregulation of ARID1A in border zone cardiomyocytes could further be confirmed in a mouse model of myocardial infarction (MI)." (PMID 37543677, 2023).
ovarian adenocarcinoma (1 paper, 2023). An adenocarcinoma that arises from the ovary. "SKOV3 was derived from ascites of ovarian adenocarcinoma and contains mutant ARID1A and PIK3CA, and is frequently more closely associated with clear-cell tumors." (PMID 37621654, 2023).
Pan (1 paper, 2020). "Similarly, ARID1A, which is characterized predominantly by the SNA type of genetic alterations, showed ConsensusDriver potential in many cancer types but did not appear among the top 100 Pan-Cancer Driver ERGs." (PMID 32963031, 2020).